LAG3 (lymphocyte activating 3)
Diseases named in the same sentence as LAG3 in open-access papers (continued):
Sharing a sentence is not in itself a finding about the gene and the disease.
cancer (continued). "It is widely established that elevated levels of cytotoxic CD8+ T cells are associated with stronger anti-tumor effect and improved prognosis in human cancers, and LAG-3 has served as inhibitory molecule to attenuate the effector function of CD8+ T cells in HCC." (PMID 32762721, 2020). "To determine whether the immune system can control these cancers, we treated mice with a combination of anti-PD-L1 and anti-LAG-3 mAb33." (PMID 32165639, 2020). "LAG-3 can regulate T cell proliferation, activation, and homeostasis, leading to consider it as a promising therapeutic candidate for immune therapy in various cancers." (PMID 32756500, 2020). "Several studies demonstrated LAG3 expression on effector CD8+ TILs in different cancer types." (PMID 32232506, 2020). "Here we explore the presence and prognostic role of LAG3 in cancer." (PMID 31681578, 2019). "In accordance with this, we found that the single blockade of PD-L1 or in combination with PD-1 did not have any beneficial effects on activated CD4+CD25+ T cells but, in fact, further increased the expression of alternate ICs, such as TIM-3 and LAG-3 (new emerging therapeutic targets for cancer)." (PMID 31614877, 2019). "Liver sinusoidal endothelial cell lectin (LSECtin) and Galectin-3 have been speculated to be additional ligands for LAG3 and have been found to be expressed on cancer cells to inhibit IFNγ secretion by CD8+ T cells." (PMID 30936880, 2019). "Accordingly, the role of LAG-3 in cancer and ESCC in particular remains elusive." (PMID 31882943, 2019). "Besides CTLA4 and PD1, LAG3 is now considered a major target for the mAb-based cancer immunotherapy." (PMID 31623599, 2019). "Thus, modulation of the LAG-3 pathway has the potential to impact autoimmunity and infections as well as cancer." (PMID 29535740, 2018). "Numbers of researchers and pharmaceutical companies have investigated antibody treatments that block these “immune checkpoint” in human, and anti-PD-1, anti-PD-L1, and anti-LAG-3 antibodies have been approved for various human cancers or evaluated on clinical trials with cancer patients." (PMID 29914540, 2018). "With the development of T cells for cancer immunotherapy, researches have revealed other immune checkpoints that significantly suppress the immune response, such as lymphocyte-activation gene 3 (LAG3), T-cell immunoglobulin mucin 3 (TIM3), and V-domain Ig suppressor of T cell activation (VISTA)." (PMID 29329591, 2018). "In addition, high LAG-3 expression on regulatory T cells (Tregs) has been reported for patients with varying cancer types, providing an additional rationale for targeting LAG-3 with the aim of reducing immune suppression within the TME." (PMID 30400822, 2018). "In HCC-vaccine-immunized mice, STAT3-blocked HCC vaccine downregulated expression of PD-1, TIGIT, and LAG-3, which could prevent cancer-induced dysfunction of CD8+ T and natural killer cells." (PMID 29843754, 2018). "In cancer and chronic viral infections, expression of LAG-3 is increased in exhausted T cells." (PMID 28545567, 2017). "Importantly, several ongoing clinical trials involve the use of anti-LAG-3 antibodies either alone or in combination with PD-1 blockade in various cancers (ClinicalTrials.gov)." (PMID 29023417, 2017). "Therefore, in both chronic viral infections and cancer, PD-1 and LAG-3 signaling pathways functionally cooperate to inhibit T lymphocytes responses." (PMID 28545567, 2017). "Inhibition of LAG-3 activity could potentially be a host-based target towards, along the lines of immunotherapies against cancer that are being developed using LAG-3." (PMID 28880895, 2017).
cancer (continued). "Similar to other exhaustion markers, LAG-3 is up-regulated in cancer and chronic infections." (PMID 28073373, 2017). "This study clearly opens new avenues for PD therapy as LAG3 antibodies are already being tested as cancer treatments and suggested that LAG3 might mediate both immune system activation and systemic spreading of pathological fibrillary α-synuclein species." (PMID 28133550, 2017). "Regarding LAG-3, this molecule is also expressed on Treg cells and has been associated with increased suppressive events, such as in the immune response against HIV and Plasmodium spp., as well as many types of cancers." (PMID 29312289, 2017). "In addition to PD-1 and TIM-3, LAG-3 is also upregulated and maintained in exhausted T cells in both chronic viral infections and cancer." (PMID 26347741, 2015). "This suggests that LAG-3 targeting may have a strong antitumor effect in some cancer types." (PMID 40606990, 2025). "Aberrant expression of LAG3, which is interdependent with its ligand FGL-1 and inhibits T-cell function, has been reported to be negatively associated with clinical prognosis in a variety of cancers, including solid tumors and some cancers of hematological origin." (PMID 40411616, 2025). "The common germline variant LAG3 rs870849 had not been previously linked to overall cancer risk." (PMID 41155207, 2025). "ICIs were grouped by mechanistic class (PD-1, PD-L1, CTLA-4, LAG-3), and additional variables included polypharmacy (number of unique drugs), sex, age, and cancer diagnosis (assigned using both indication keywords and manual curation of cancer-specific medications)." (PMID 40630567, 2025). "Immune checkpoint inhibitors (ICIs), as vigorous weapons against cancer cells, have revolutionized clinical immunotherapy approaches by targeting specific receptors on immune cells such as PD-1, cytotoxic T-lymphocyte–associated protein 4 (CTLA-4), TIM3, and lymphocyte activation gene 3 (LAG-3)." (PMID 41291696, 2025). "Finally, future studies could compare the efficacy of Nano-Gefitinib with other targeted therapies or checkpoint inhibitors (e.g., anti-FGL1/LAG-3 blockade) to determine whether combinatorial regimens yield synergistic benefits in cancer therapy." (PMID 41304988, 2025). "Importantly, a potential factor in resistance to anti–PD-1/anti–PD-L1 immunotherapies in cancer is LAG-3 and PD-1 co-expression, which may lead to significant T-cell dysfunctionality." (PMID 38590525, 2024). "Suppose PDL1 (like LAG3) is not only a CPI but also a stemness marker (unlike other CPI), could that explain why anti-PD1/L1 (and anti-LAG3) is a better anti-cancer treatment compared with those other CPI (e.g., anti-CTLA4, anti-IDO1, anti-TIGIT), which are bona fide immunotherapy?" (PMID 38539487, 2024). "Interestingly, SPAG5 overexpression was correlated with high levels of lymphocyte CD8+, macrophages, neutrophils, dendritic and B cells, positively associated with PD-1/PDL1, LAG3, GZMB and CTLA4 and SPAG5 antigens were suggested as valid immune stimulatory targets for anti-cancers therapy." (PMID 39164278, 2024). "Therefore, might utilizing three ICIs specifically targeting PD-1/PD-L1, CTLA-4, and LAG-3 provide a better alternative for cancer patients?" (PMID 38390331, 2024). "This suggests that targeting LAG-3 could have a substantial antitumor impact in these cancer types." (PMID 38375475, 2024). "Consequently, it is crucial to investigate the role of LAG3 in distinct cancer types individually." (PMID 38277212, 2024). "Furthermore, this finding indicates that LAG-3 methylation could be a promising target for interventions in cancer treatment." (PMID 38390331, 2024). "The successful application of LAG-3 inhibitors like Relatlimab in combination with PD-1 inhibitors like Nivolumab opens up avenues for further exploration of other T-cell molecules that might play a role in immune response inhibition against cancer." (PMID 39155358, 2024).
cancer (continued). "The successful application of LAG-3 inhibitors like Relatlimab in combination with PD-1 inhibitors like Nivolumab opens avenues for further exploration of other T-cell molecules that might play a role in immune response inhibition against cancer." (PMID 39155358, 2024). "Therefore, serum LAG3 might predict both therapeutic and adverse effects of ICIs in cancer patients." (PMID 38776028, 2024). "Furthermore, we assessed the prognostic implications of LAG3 genetic alteration in cancer patients." (PMID 38115039, 2023). "Our data show that GB265, GB266, and GB266T have superior performance to these antibody combinations in assays that mimic the general characteristics of the TME, and could represent a better approach to target the PD-1, TIGIT and LAG-3 immune checkpoints in immunotherapy of cancers." (PMID 37332070, 2023). "Higher levels of CD163, CD14, Fibronectin, B7-H3, LAG3, Tim-3, PD-L1, VISTA, CD25, and CD44 associated with fibroblasts, myeloid-derived cells, T cells, and NK cells were found in the ‘surrounding stromal leukocytes’ cf. ‘immune-rich cancer cell islet’ regions." (PMID 37046826, 2023). "The most widely used immunotherapies that have proven clinical efficacy across a wide range of cancers are immune checkpoint inhibitors (ICIs) targeting programmed cell death 1 (PD-1), PD-L1, cytotoxic T lymphocyte-associated antigen 4 (CTLA-4) and lymphocyte activation gene-3 (LAG-3)." (PMID 36945046, 2023). "As our findings show that there is a significant proportion of LAG3+ CD8+ T-cell targeted by ligand LGALS3+ originating from mesenchymal cancer cells, we sought to further explore the link between LGALS3 and EMT to better elucidate how EMT could modulate CD8+ T-cell exhaustion." (PMID 38086828, 2023). "Therefore, we conducted this study to determine whether LAG3 is a potential prognostic biomarker for various cancers or a molecular therapeutic target for MPM." (PMID 38062416, 2023). "Additionally, LAG3 combined with PD-1/PD-L1 may serve as a predictor of immunotherapy treatment effectiveness in primary pulmonary lymphoepithelioma-like carcinoma." (PMID 38041068, 2023). "Therefore, to overcome the resistance of PD-1 blockade in resistant cancers, the synergistic blockade of Lag-3 and PD-1 may provide a promising therapy." (PMID 36159789, 2022). "This suggests that LAG3 inhibitors may have a therapeutic potential in these cancers." (PMID 36224560, 2022). "Moreover, LAG-3 expression correlates with poor prognosis in many cancers." (PMID 36135216, 2022). "Moreover, the combination of LAG-3 and PD-1 blockade has good clinical efficacy in cancers." (PMID 35494015, 2022). "In addition, a pan-cancer study highlighted that altered PARP1 was correlated with the high degree of immune cell infiltrations, such as CD8+ T cells, in most cancers, simultaneously, there were higher expression levels of PD-1, LAG3, and CTLA-4 in the PARP1-altered group." (PMID 36818471, 2022). "Therefore, LAG3 is suitable as a clinical target to block cancer progression." (PMID 35279104, 2022). "Additionally, given that CRC is a cancer with high expression of LAG3, targeting LAG3 may be an excellent therapeutic approach to treat such solid tumors." (PMID 35711437, 2022). "Thus, LAG-3 is a good candidate for targeted therapy for a wide range of cancers." (PMID 36140182, 2022). "On the other hand, reduced engagement of the inhibitory co-receptors LAG3, a novel immunotherapeutic target in cancer and particularly B lymphomas, or FCRL6, due to decreased expression of its MHC-II ligand, could contribute to explaining the enhancement of anticancer immune responses by ICD." (PMID 36009442, 2022). "Further studies on whether TIM-3 and LAG-3 are regulated by other acetylation/deacetylation molecules and the specific signaling pathways may provide novel targets and therapeutic strategies for future cancer immunotherapy." (PMID 35585975, 2022).
cancer (continued). "Therefore, LAG3 blockade combined with MWA might be employed in the clinical setting to reprogram the TME in an anti-cancer manner, revealing the potential value of the clinical application." (PMID 36180876, 2022). "However, a number of new ligands for LAG-3 have been recently described that may help to provide insights into the impacts of LAG-3 on immune responses in cancer." (PMID 34068762, 2021). "Additionally, in cancer models, the synergy between LAG-3 and PD-1 has been noted." (PMID 34575943, 2021). "Hence, more research is required to verify the predictive value of LAG3 in these cancer types." (PMID 35111155, 2021). "From these studies, it can be concluded that DNA and histone modifications are certainly involved in LAG-3 upregulation in cancer, suggesting that epigenetic modifications could be useful as a potential predictive biomarker of response to immune checkpoint blockade immunotherapies." (PMID 34067904, 2021). "However, the expression of other T-cell inhibitory receptors, such as Tim-3 (Havcr2) or Lag-3, and the cancer immune evasion-related factor Pak4 remained unchanged in MUP-uPA mice, regardless of the type of diet fed in parallel to the unchanged expression of indoleamine 2,3-dioxygenase (Ido1)." (PMID 34439245, 2021). "Similarly to PD-1, constitutive LAG-3 expression is frequently associated with exhausted T cells, and it is generally regarded as an exhaustion marker for CD4 and CD8 T cells in response to repetitive antigen stimulation in cancer and chronic viral infections." (PMID 34067904, 2021). "Although the most advanced knowledge has been generated around the therapies targeting PD-1/PDL-1 or CTLA-4, there are multiple other important pathways that may impact the immune response to cancer involving many genes, in particular LAG-3, TLR-4, VISTA, TIM-3, TIGIT, ICOS, OX40, and GITR5." (PMID 33911192, 2021). "Thus, agents that target alternative co-inhibitory pathways, such as anti-CTLA-4 antibody and anti-LAG3 antibody, may be effective in cancers with a T3 TIME." (PMID 32245497, 2020). "In particular, the cancer cells bind and activate the co-inhibitory molecules on the T lymphocyte surface, e.g., T lymphocyte-associated antigen 4 (CTLA4), programmed cell death protein 1 (PD1), lymphocyte activation gene 3 (LAG3) and T cell immunoglobulin mucin 3 (TIM3)." (PMID 28635639, 2017). "As one of our primary goals was to investigate the potential importance of ICRs in γδ T cell subsets in health and in cancer, we additionally assessed expression of PD-1, TIM-3, LAG-3, TIGIT and CTLA-4 by flow cytometry in all patients." (PMID 41310392, 2026). "In support of this, it has been described that the expressions of LAG-3, TIM-3 and PD-1 identify antigen-experienced T cells in cancer patients." (PMID 41051510, 2025). "Our research shows that PIEZO1 expression is positively correlated with key immune checkpoints, including CD274 (PD-L1), CTLA4, LAG3, PDCD1 (PD-1), PDCD1LG2 (PD-L2), and TIGIT across various cancer types." (PMID 40977743, 2025). "In support of this, coculture experiments have shown that HLA-DRhi cancer cells upregulate the inhibitory receptor expression on CD8+ T cells, including PD-1, LAG-3, and TIM-355." (PMID 41281745, 2025). "Other immune checkpoints, such as LAG-3, TIM-3, and TIGIT, are under exploration as cancer immunotherapy and can possibly be integrated into liposomal delivery systems for more efficient cancer targeting." (PMID 40872479, 2025). "Another LAG-3 functional ligand, FGL1, was shown to be highly expressed in a variety of cancers, such as melanoma, lung cancer, and colorectal cancer." (PMID 40846797, 2025). "The correlation between SLC2A1 expression and eight immune checkpoints (CTLA4, PDCD1, TIGIT, LAG3, CD274, HAVCR2, PDCD1LG2, and SIGLEC15) was further investigated across multiple cancer types." (PMID 40824962, 2025).
cancer (continued). "We found significant differences in the expression of SELENOP, PKMYT1, LAG3 and CD244 between the cancer tissues and adjacent cancer tissues." (PMID 40821907, 2025). "Emerging strategies including novelcheckpoint targets (e.g., LAG-3, TIGIT), next-generation cellular therapies, cancer vaccines, and oncolytic viruses areunder active investigation to expand therapeutic options and improve patient outcomes." (PMID 41170078, 2025). "Currently, a dual CXCR1/2 inhibitor, SX-682, is being evaluated in combination with LAG-3 blockade and CD137 agonists or in combination with PD1 blockade in the context of surgically resectable cancer." (PMID 40723238, 2025). "More recently, lymphocyte activation gene 3 (LAG-3) has emerged as a next-generation immune checkpoint, offering promising potential for advancing cancer therapy." (PMID 41112277, 2025). "Previous studies have highlighted the differential expression patterns of HAVCR2, TIGIT, LAG3, LAYN, and CXCL13, showing strong correlations with survival outcomes across multiple cancer types." (PMID 40076932, 2025). "Antibodies targeting immune checkpoints, such as PD1, PDL1, and LAG3, have been approved by FDA for cancer therapy." (PMID 40744688, 2025). "Cancer cells often evade immune surveillance by exploiting immune checkpoint receptors, such as TIM-3, LAG-3, CTLA-4, and PD-1." (PMID 40870970, 2025). "We examined the relationship between EIF5A2 and immune checkpoints using Spearman analysis and found that EIF5A2 was correlated with CD274, PDCD1LG2, and HAVCR2 in the majority of cancers and PDCD1, CTLA4, LAG3, SIGLEC15, and TIGIT in some tumors." (PMID 40964657, 2025). "The mRNA expression profile of six Tex markers, LAG-3, PDCD1, TIGIT, HAVCR2, CXCL13, and LAYN was investigated in pan-cancer." (PMID 40076932, 2025). "KIRC also shows the highest level of T-cell exhaustion, indicated by increased activity of immune checkpoint molecules like FASLG, CTLA4, PDL1, PD1, LAG3, and TIM3, which are involved in immune suppression in cancer." (PMID 40649942, 2025). "In chronic infections (e.g., HIV, HCV) and cancer, multiple coinhibitory receptors, including PD-1, CTLA-4, LAG-3, TIM-3, and TIGIT are upregulated on Tex." (PMID 40236693, 2025). "LAG-3 is co-expressed and engages in crosstalk with other immune checkpoints, including PD-1 and CTLA-4, in various cancer types." (PMID 39751894, 2025). "For instance, increased expression of inhibitory checkpoints such as LAG-3, TIGIT, and TIM-3 has been documented in various cancers." (PMID 40805205, 2025). "We further found that ITGA4 was positively correlated with most immune regulatory molecules across cancers, such as CTLA4, PDCD1, LAG3, which inhibit T cell activity." (PMID 40012546, 2025). "Among 60 ICP genes, including 24 immune inhibitors (such as CTLA4, LAG3, or VEGFB) and 36 activators (TNFRSF9, CD28, or TNFRSF9, etc.), we found DHCR7 played roles both in inhibitors and activators of ICP in human cancers." (PMID 41198144, 2025). "When co-culturing Gal-9 overexpressing cancer cells with T cells, we observed a significant increase in the percentage of CD8+PD1+, CD8+PD1+Tim3+, and CD8+PD-1+Tim-3+Lag-3+ T cell populations." (PMID 40666515, 2025). "In this review article, we provide a comprehensive survey of the biological mechanisms of ICPs that are most frequently targeted in cancer therapy, including CTLA-4, PD-1, PDL-1, and LAG3." (PMID 39359534, 2024). "We investigated the methylation levels (beta values) of TIGIT, CXCL13, LAYN, LAG3, PDCD1, and HAVCR2 across different cancer types." (PMID 39064019, 2024). "Regarding the classical cell-surface inhibitory receptors PD-1 and Lag-3, we certainly observed parallel expression with KLRG1, as has been reported in some infections and cancers." (PMID 38776335, 2024). "Relatlimab (BMS-986016, Opdualag, Bristol-Myers Squibb Company), a first-in-class anti-LAG-3 blocking antibody, represents the third approval of ICB-based therapy for patients with cancer." (PMID 39425148, 2024).